NLRC4 (NLR family CARD domain containing 4)
Diseases named in the same sentence as NLRC4 in open-access papers (continued):
Sharing a sentence is not in itself a finding about the gene and the disease.
infection (continued). "A diminished expression of NLRC4 could result in dysregulation of these pathways, adversely affecting cellular responses to infections and pathogen clearance." (PMID 39292002, 2024). "The Leishmania promastigote stage has a flagellum that could potentially be recognized by the ASC-independent NLRC4 inflammasome, however, infection of Nlrc4-/- and control mice resulted in similar pathology." (PMID 39250503, 2024). "Similarly, Casp1/11+/–Casp8–/–Ripk3–/– mice retain the ability to recruit Caspase-1 to NLRC4 and to initiate cell death via Caspase-11 and should also thus be resistant to infection." (PMID 36645406, 2023). "In contrast, BMDMs deficient in NLRC4 had no cell death and significantly reduced IL-18 release in response to these infections." (PMID 37557956, 2023). "Additionally, the NLRC4 inflammasome (along with the NLRP3 inflammasome) were involved in immune responses against Candida albicans in a murine model of infection." (PMID 37006312, 2023). "To delve deeper into the potential contribution of the NAIP/NLRC4 inflammasome during T. cruzi infection on macrophages, we assessed intracellular parasites count at 2 h (parasite entry) and 96 h (parasite replication load) after infection." (PMID 38124741, 2023). "For the entirety of this study, we infected bone marrow-derived macrophages (BMDMs) with mutant L. pneumophila deficient for flagellin (ΔflaA) in order to bypass the NAIP5 inflammasome response and specifically examine the NAIP5/NLRC4-independent role of TNF signaling in control of infection." (PMID 37279255, 2023). "In (F–O), B6.Nlrc4–/–Casp11–/– mice received 200 μg of either TNFα neutralizing antibody (teal, n=12) or isotype control antibody (maroon, n=13) by intraperitoneal injection daily from 1 day before infection through sacrifice at 2 days post-infection." (PMID 36645406, 2023). "Casp1/11–/–Casp8+/–Ripk3–/– mice retain Caspase-8 function downstream of both NLRC4 and TNFα and based on our previous experiments with Casp1/11–/– mice, we expected that these mice would be resistant to infection." (PMID 36645406, 2023). "After infection of THP-1 cells with S. mutans there was an increase in the inflammasome expression associated with IL-1β secretion through activation of caspase-1, NLRP3, and NLR family CARD domain-containing 4 (NLRC4)." (PMID 35893249, 2022). "For these experiments, we selected a time point later in the infection to ascertain whether any ExoU-mediated effects occur after the NLRC4 inhibition has been relieved." (PMID 35130452, 2022). "The P. aeruginosa T3SS needle tip complex and flagellin are PAMPs that specifically activate the intracellular nucleotide-binding domain containing leucine rich repeats-like receptor 4 (NLRC4)/NLR family apoptosis inhibitor proteins (NAIP) inflammasome complex during infection (35, –, 38)." (PMID 35130452, 2022). "Inflammasomes, including NLRP3 and NLRC4, are detected during infection, and flagellin in bEVs may be a key ligand for NLRC4 inflammasome activation." (PMID 35693784, 2022). "Current literature suggests that NLRC4 and caspase-11 are activated at different timelines during melioidosis, in which NLRC4 activates pyroptosis in early phases of infection and induces IFNγ, reducing intracellular bacterial load and possibly primes caspase-11." (PMID 35626718, 2022). "Under SPI-II inducing conditions, the NLRC4 inflammasome only contributed significantly toward IL-1β secretion, and its ablation did not significantly protect against the induction of cell death after infection." (PMID 34864057, 2022). "Compared to GSDMD-deficient mice, deletion of NLRC4 alone showed an increase in tissue damage and weight loss during infection but no significant increase in the bacterial burden." (PMID 35801644, 2022). "In addition to the direct binding of bacterial ligands by NAIP proteins, other regulatory mechanisms participate in NAIP/NLRC4 activation under infections or sterile condition." (PMID 36481780, 2022).
infection (continued). "P. aeruginosa ExoU transiently inhibits NLRC4 inflammasome activation during infection of BMDMs." (PMID 35130452, 2022). "In addition, AIM2 knockout mice are more susceptible to Brucella infection and infection of C57BL/6, NLRC4, NLRP3, AIM2, ASC and Caspase-1 KO (knockout) BMDM (bone marrow-derived macrophage) with B. abortus than wild-type control mice." (PMID 36068262, 2022). "It remained unknown how this NAIP/NLRC4-dependent tradeoff would develop during subsequent infection stages." (PMID 33731826, 2021). ".Tm infection, we studied the impact of NLRC4-ablation over the entire 72 h." (PMID 33731826, 2021). "Second, we cannot exclude the possibility that the non-AIM2-dependent signaling pathway may be induced to compensate for the impaired autophagy flux, such as the NLRC4-dependent way in infection-induced autophagy or the NLRP3 inflammasome–autophagy crosstalk." (PMID 34740380, 2021). "Additionally, NLRC4 is up-regulated in immune and inflammatory cells after infection of diverse bacteria, such as Salmonella typhimurium, K. pneumoniae, L. pneumophila, P. aeruginosa, Burkholderia pseudomallei, and E. coli." (PMID 33553427, 2021). "Our work uncovers a central role of epithelium-autonomous NAIP/NLRC4 in eliciting a fine-tuned early response to the infection, thereby preventing the demise of the epithelial barrier, due to an overshooting pro-inflammatory TNF response in the intestinal mucosa." (PMID 33731826, 2021). "In unprovoked macrophages, NLRC4 has been shown to be important in controlling infection." (PMID 34276697, 2021). "T3SS1 effector SopB was found to inhibit the activation of NLRC4 inflammasome during ST infection." (PMID 32723297, 2020). "Under the infection of Salmonella, NLRC4 and NLRP3 inflammasomes could be activated within 1 h, cut the pro-caspase-1 into active caspase-1 in macrophages and induce pyroptosis." (PMID 33324360, 2020). "To further characterize the role of the NAIP–NLRC4 inflammasome during Shigella infection of IECs, we generated intestinal epithelial stem cell-derived organoids from the ceca of 129.WT and 129.Nlrc4–/– mice and established a transwell monolayer infection assay." (PMID 33074100, 2020). "Therefore NAIP/NLRC4 inflammasomes are considered to be crucial regulators of infection and immunity." (PMID 32630319, 2020). "In this study, we found that the survival rate of PA+NLRC4−/− mice was significantly improved compared with PA+WT mice and PA+NLRP3−/− mice, suggesting that the activation of NLRC4 inflammasome may aggravate infection and increase mortality." (PMID 33489931, 2020). "This genetic approach was not only useful for supporting the previously published association of the NLRP3 rs10754558 variant with Mtb infection, but also for revealing that NLRC4 could be another genetic factor important for the outcome of infection." (PMID 33193317, 2020). "Notably, the restriction of systemic bacterial loads by epithelial NAIP/NLRC4 was equally relevant in an infection with a different S. Tm strain (S. Tm14028)." (PMID 31953493, 2020). "Counter to these pro-infection concepts, intracellular flagella are activators of innate responses via the NLRC4 inflammasome and S. Typhimurium flagella activation of NLRC4 is known to induce actin-dependent host cell surface stiffening to prevent further bacterial invasion in macrophages." (PMID 32886602, 2020). "Interestingly, Nlrc4−/− mice phenocopied Il22−/− mice as IL-18 levels were unaffected in the early phase of the infection but dramatically reduced in the later phase, consistent with previous findings showing that IL-22 and NLRC4 works along the same pathway." (PMID 31681274, 2019). "In our study, we have found NLRC4 activation in response to CFT073 infection and thus we may conclude that this activation could be due to the presence of flagellin and T3SS of CFT073." (PMID 31551961, 2019).
infection (continued). "Since NLRC4 can be upregulated by lipopolysaccharide (LPS) in human neutrophils, it is conceivable that longer infections could lead to IL-1β production by neutrophils in response to P. aeruginosa." (PMID 30455194, 2019). "However, infection with Salmonella typhimurium, activator of the NLRC4 inflammasome, led to caspase-1 activation and increased IL-1β production in BMDMs from Lgal3−/− mice." (PMID 31406212, 2019). "NLRC4-mediated inflammasome activation was also examined using Salmonella mutant infection." (PMID 31708887, 2019). "In this report by Liu and colleagues, they showed that the activation of inflammasomes containing NLR family CARD domain-containing protein 4 (NLRC4) in response to the infection of pathogens was insufficient in Lrrk2 KO macrophages, leading to the reduced production of IL-1β." (PMID 32714591, 2018). "Thus, P. aeruginosa T3SS effector protein ExoU can inhibit activation of the NLRC4 inflammasome and caspase-1 and, as a result, downregulates rapid neutrophil recruitment and rapid infection clearance." (PMID 30276212, 2018). "It was previously demonstrated that the production of PGE2 induced by flagellin injection or S. Typhimurium infection was attenuated in cells that do not express NLRC4, which suggests that the presence of NLRC4 inflammasome is critical for the induction of PGE2 biosynthesis during infection." (PMID 30429830, 2018). "However, Salmonella can escape the NLRC4 detection in the late stage of infection for its survival in macrophages." (PMID 29523140, 2018). "Data from our previously published studies suggest that multiple inflammasome complexes including NLRP3, AIM2, and NLRC4 are upregulated during infection with virulent Ehrlichia and may play a role in the development of Ehrlichia-induced liver injury." (PMID 29049365, 2017). "Our data suggest that caspase-8 activation in the Naip5/NLRC4/ASC inflammasome may favor host responses during infections against pathogens that inhibit components of the pyroptotic cell death including caspase-1 and gasdermin-D." (PMID 28771586, 2017). "Mice lacking components of the NLRP3- or NLRC4- inflammasome have been found to be more susceptible to infection by various bacterial pathogens." (PMID 27617233, 2016). "Moreover, ASC has been demonstrated to change the subcellular localization of Nlrc4 and caspase-1 upon infection via recruitment to discrete puncta structures which is important not for the activation but for the cleavage of caspase-1." (PMID 27148204, 2016). "Since bacterial clearance after recognition of flagellin via Nlrc4 also applies for other non-pneumophila Legionella species it is likely to be a general mechanism of host protection against infections caused by Legionella ssp." (PMID 27148204, 2016). "Dissection of the contributions of the cellular compartments has revealed that cecum-derived E-cadherin+ intestinal epithelial cells (IEC) express high amounts of ASC adaptor, and Nlrp3 and Nlrc4 activation are both critical for protection against C. rodentium early in the course of infection." (PMID 27617233, 2016). "This IL-1β production in response to infection with KIM5 ΔYopK was eliminated in NLRP3/NLRC4 deficient cells, but was independent of Pyrin." (PMID 27911947, 2016). "In addition, a recent study has shown that these neutrophils are able to sustain IL-1β production during acute ST infection due to their unique resistance to pyroptotic cell death on NLRC4 inflammasome activation." (PMID 27363812, 2016). "In contrast, the expression of NLRC4 persistently increased in C57BL/6 mice through the infection." (PMID 26972847, 2016). "Two inflammasome complexes, NLRP3 and NLRC4, are required to fully combat infection." (PMID 27011353, 2016). "In accordance, we found that NLRC4 and caspase-1 are important for induction of pyroptotic cell death regulating intracellular growth of Burkholderia early in the infection process." (PMID 24626296, 2014).
infection (continued). "Although the NLRC4 inflammasome has been shown to be activated by flagellated Gram-negative bacteria, recent studies have shown evidence for a flagellin-independent pathway that activates the NLRC4 inflammasome after infection with certain aflagellated bacteria." (PMID 25540075, 2014). "Our work also shows the activation of caspase-9 and -7 and cleavage of PARP downstream of NLRC4/caspase-1 inflammasome in the early phase of infection by B. pseudomallei and a possible role for caspase-1-dependent and -independent cell death mechanisms at later time points." (PMID 24626296, 2014). "Moreover, many receptors and adaptors are downregulated after infection with WT parasites only: Dectin-1 (Clec7a), IL-1 receptor type I, Nlrc4 and Trem1." (PMID 24736445, 2014). "Furthermore, infection with Shigella preferentially promoted the interaction of Nlrc4 with Naip2 relative to Naip5." (PMID 24516390, 2014). "These effector mechanisms mediated by NAIP/NLRC4 inflammasomes have been extensively studied in the context of resistance of infections and the potential of their agonists has been exploited in therapeutic strategies to non-infectious pathologies, such as tumor protection." (PMID 25071770, 2014). "We could show that upon infection of macrophages, caspase-7 is activated downstream of the NLRC4/caspase-1 inflammasome and requires caspase-9 processing." (PMID 24626296, 2014). "Although the possible targets of caspase-1 and caspase-11 mobilized during pyroptosis remain unidentified, the studies involving NAIP/NLRC4 hugely contribute to the idea that this inflammatory form of cell death is an important effector mechanism against infections." (PMID 25071770, 2014). "Rapid NLRC4- and caspase-1-dependent cell death in wild-type macrophages at high MOI led to high LDH release within the first hours after infection compared to NLRC4 and caspase-1/11 knockout macrophages, which exhibited signs of cell death as recently as 24 hours." (PMID 24626296, 2014). "In contrast, our study showed that infection of wild-type and NLRP3 knockout macrophages but not NLRC4-deficient macrophages with B. pseudomallei E8 leads to activation of caspase-1 and downstream signalling pathways at 1.5 hours after infection." (PMID 24626296, 2014). "In addition gene set enrichment analysis (GSEA) was performed using a 25% false discovery rate cutoff and no gene sets were noted to be significantly different in the lungs of Nlrc4−/− mice compared to WT after infection with LP." (PMID 23937571, 2013). "Concurrently, Dixit and colleagues reported the generation of the first inflammasome knockouts, namely mice deficient in IPAF (NLRC4) or the adaptor ASC, and showed that macrophages from these mice had a defect in IL-1β production following infection with flagellated bacteria." (PMID 24137163, 2013). "NAIP5 and NLRC4 also contribute to the control of L. pneumophila replication by enhancing fusion of the Legionella-containing vacuole (LCV) with lysosomes during infections performed at a low multiplicity of infection (MOI)." (PMID 24409420, 2013). "However, little is known if genes downstream of NLRC4 control replication in the lungs during in vivo infection." (PMID 23937571, 2013). "In addition our study reveals elevated TNF and CXCL2 at 24 hours post-infection in Nlrc4−/−/Tlr5−/− mice compared to Nlrc4−/− and WT mice." (PMID 23937571, 2013). "We next sought to determine whether IL-1α is also released independently of ASC and NLRC4 during in vivo infection." (PMID 23762026, 2013). "Infection of macrophages with the pathogen typhimurium is known to activate the NLRC4 inflammasome." (PMID 22105559, 2012). "Using bone marrow chimeric mouse models, we show that, in contrast to NLRP3 which limits the severity of infection when present in either the hematopoietic or stromal compartments, NLRC4 plays an important role in limiting mucosal candidiasis when functioning at the level of the mucosal stroma." (PMID 22174673, 2011).
infection (continued). "Infection of macrophages with Salmonella typhimurium, Shigella flexneri, Legionella pneumophila, and Pseudomonas aeruginosa all induce IL-1β secretion via activation of an NLRC4 inflammasome." (PMID 22019906, 2011). "We now show that, in addition to the NLRP3 inflammasome, a different inflammasome containing NLRC4 is also important in protecting against infection with Candida albicans, and appears to be functioning in the mucosal lining of the mouth and intestines, rather than in immune cells." (PMID 22174673, 2011). "Lack of NLRC4 also increased susceptibility to disseminated fungal infection, particularly early in infection." (PMID 22174673, 2011). "However, later in the infection process (8 hours) Nlrc4-/- cells secreted IL-1β at levels considerably higher than WT cells." (PMID 22241982, 2011). "Current models of NLRP3 activation indicate it does not act as a traditional receptor but rather as a nexus for different pathways invoked following cellular injury and/or infection, which may also be true for the NLRC4 inflammasome." (PMID 22174673, 2011). "However, at 96 h post-infection Naip1-7-/- and Nlrc4-/- PMs were more permissive to T. cruzi replication than C57BL/6 WT cells, presenting higher frequency of infected cells and higher numbers of intracellular amastigotes in comparison to their littermate control cells." (PMID 38124741, 2023). "Conversely, phosphomimetic NLRC4 S533D caused rapid macrophage pyroptosis without infection." (PMID 35800898, 2022). "Thus, further studies are required to fully delineate whether the timing or subcellular localization of ExoU and/or the NLRC4 inflammasome play a biological role during infection." (PMID 35130452, 2022). "NLRC4 has also been found to play an important role in driving human autoinflammatory disease, those diseases caused by systemic or organ-specific inflammation that is not attributable to infection, malignancy, or antigen-specific autoimmunity." (PMID 34276697, 2021). "Thus, a novel therapeutic approach may be provided by modulating the function of the NLRC4 for the treatment of bacteria-induced infections in the lungs in the future." (PMID 33553427, 2021). "Also, PA infection induced an increase in NLRC4 mRNA in lung as measured by real time RT-PCR." (PMID 33489931, 2020). "Interestingly, in Nlrc4–/– mice, IL-1β and KC levels in target tissues are elevated, indicating that Shigella may encounter multiple inflammasomes at distinct stages of infection with opposing consequences for bacterial replication and host pathogenesis." (PMID 33074100, 2020). "However, the defective NLRC4 phosphorylation in CF could be restored by blocking the increased calcium signalling of CF airway epithelia 29, a finding pointing to the complexity of NLRC4 activation in vivo during infection." (PMID 26972847, 2016). "Infection with mT3Sf::empty induced cell death of infected THP-1 human macrophages, and this death was reduced in CASP4/NLRC4–/– double knockout cells to the background levels seen in control GSDMD–/– cells." (PMID 41533441, 2026). "If human IECs express low NAIP–NLRC4 levels, p38-dependent rapid priming would be essential for a protective NAIP–NLRC4 response and would be potently blocked by OspF during infection, as observed in THP-1 cells with low NLRC4 expression." (PMID 41533441, 2026). "Similar to the NAIP/NLRC4 inflammasome, GSDMD is required for the protection against infection of IECs at 18 h post infection." (PMID 40796289, 2025). "When mouse BMDMs are infected with S. Typhimurium at a multiplicity of infection (MOI) of 1, the kinases PKC-δ and LRRK2 phosphorylate NLRC4 at S533." (PMID 41062723, 2025). "In this study, we found that in the infection model of THP-1 derived human macrophages, which express multiple inflammasomes, E. tarda induced pyroptosis in a manner that depended on NLRC4, NLRP3, ASC, Casp1, and Casp4." (PMID 39951384, 2025).